ROCK2 (Rho associated coiled-coil containing protein kinase 2)
Diseases named in the same sentence as ROCK2 in open-access papers (continued):
Sharing a sentence is not in itself a finding about the gene and the disease.
colon cancer (6 papers, 2014 to 2022). "ROCK2 is overexpressed and associated with increased invasion and poor survival in several tumors, including colon cancer." (PMID 34959725, 2021). "Interestingly, ROCK1 expression is higher in leukemia and lymphoma cell lines, compared to other types of cancer cell lines, whereas ROCK2 expression is the highest in colon cancer cells." (PMID 35365653, 2022). "Moreover, ROCK2 was found to mediate invasion of colon cancer cells." (PMID 34959725, 2021).
endothelial dysfunction (6 papers, 2015 to 2025). In vascular diseases, endothelial dysfunction is a systemic pathological state of the endothelium (the inner lining of blood vessels) and can be broadly defined as an imbalance between vasodilating and vasoconstricting substances produced by (or acting on) the endothelium. "Meanwhile, in vitro knockdown of FGFR1 by siRNA activated ROCK2, leading to endothelial dysfunction with increased adhesive properties and permeability in TNFα-treated HUVECs." (PMID 36969192, 2023). "Consistent with previous work, we found that Ang II‐induced endothelial dysfunction (in both sexes and in mice on different genetic backgrounds) was prevented by acute inhibition of ROCK2." (PMID 35681278, 2022). "TDI01 effectively suppressed ROCK2 activity and rescued the endothelial dysfunction." (PMID 36969192, 2023). "In this context, our findings provide the first evidence that ROCK2 may be a key contributor to endothelial dysfunction in both sexes and in genetic strains that differ in relation to other major aspects of vascular disease." (PMID 35681278, 2022). "ROCK1 and ROCK2 exert different roles in endothelial dysfunction." (PMID 32610588, 2020). "Therefore, ROCK2 represents an attractive target for studying critical regulators of endothelial dysfunction." (PMID 32610588, 2020). "Tissue-specific and inducible gene expression studies may offer additional insights into the spatial and temporal in vivo contribution of ROCK2 to endothelial dysfunction and provide further avenues of investigation." (PMID 30884801, 2019). "Because inadequate trophoblast invasion and endothelial dysfunction are important features in the development of preeclampsia, and because SSRI-treated women had increased levels of ROCK2 in trophoblasts it may be speculated that NGF signaling also plays a role in preeclampsia." (PMID 25611484, 2015).
idiopathic pulmonary fibrosis (6 papers, 2019 to 2025). Idiopathic pulmonary fibrosis (IPF) is a nonneoplastic pulmonary disease that is characterized by the formation of scar tissue within the lungs in the absence of any known cause. "Ongoing clinical studies explore additional therapeutic indications, including idiopathic pulmonary fibrosis, systemic sclerosis, and other autoimmune diseases characterized by ROCK2-driven fibrosis." (PMID 41377066, 2025). "Zelasudil (Redx Pharma, Cheshire, UK), a next-generation ROCK2-preferential inhibitor, has shown anti-fibrotic activity in preclinical models and is currently under investigation in a phase II clinical trial for idiopathic pulmonary fibrosis." (PMID 41377066, 2025). "TDI01 is a novel and highly selective ROCK2 inhibitor that is currently being tested in phase I clinical trials for the treatment of idiopathic pulmonary fibrosis and silicosis." (PMID 36969192, 2023). "A previous study found that reduced expression of ROCK1 or ROCK2 was sufficient to protect mice from experimental pulmonary fibrosis." (PMID 37864185, 2023). "This study demonstrates that ROCK1 and ROCK2 could protect mice from bleomycin pulmonary fibrosis induction." (PMID 34830058, 2021). "Inhibition of ROCK-2 protected ROCK-2-haploinsufficient mice from bleomycin-induced myofibroblast differentiation and pulmonary fibrosis, while its activation was implicated in the development of idiopathic pulmonary fibrosis." (PMID 31814833, 2019). "Indeed, ROCK1 and ROCK2 have been the target of studies in pulmonary fibrosis." (PMID 34830058, 2021).
non-small cell lung carcinoma (6 papers, 2016 to 2022). A group of at least three distinct histological types of lung cancer, including non-small cell squamous cell carcinoma, adenocarcinoma, and large cell carcinoma. "ROCK2 was found to be commonly mutated in non-small cell lung cancer by whole-exome sequencing, and its copy number and gene expression were increased in malignant peripheral nerve sheath tumors." (PMID 26725045, 2016). "In non-small cell lung carcinoma, suppression of ROCK1 or ROCK2 expression alone was sufficient to impair anchorage-independent growth." (PMID 26725045, 2016).
Obesity (6 papers, 2018 to 2025). Accumulation of substantial excess body fat. "In another study, ROCK2 was suggested as a exacerbating factor in adipose tissue to cause obesity-induced insulin resistance as evidenced by the fact that adipocyte hypertrophy and inflammatory cytokines might mediate this exacerbation." (PMID 29410516, 2018). "Considering recent advances in understanding RhoA/ROCK signaling in regulating metabolic functions, promoting brown adipogenesis and browning process of WAT by ROCK inhibition, particularly ROCK2 inhibition, have emerged as promising strategies to treat obesity and its related metabolic disorders." (PMID 35769086, 2022). "Also, the level of RhoA protein in skeletal muscle, an upstream mediator of ROCK2, was reduced by obesity." (PMID 34234788, 2021). "Thus, inhibition of RhoA/ROCK2 in adipose tissue may provide a potential therapeutic strategy to combat obesity and insulin resistance." (PMID 35769086, 2022). "As partial deletion of ROCK1 or ROCK2 has been found to attenuate high-fat-diet obesity-induced insulin resistance, the use of Y27632 in patients suffering from obesity could be a strategy to decrease AdEV release and reduce cardiovascular diseases associated with obesity." (PMID 33670146, 2021). "Besides evaluating whether diet-induced obesity reduces the Rho-ROCK2 signaling pathway in skeletal muscle, we tested the possibility that physical exercise can restore this effect." (PMID 34234788, 2021). "ROCK2+/- mice on HFD demonstrated increased sensitivity to the browning effects of beta-adrenergic stimulation, increased energy expenditure with reduced obesity, and improved insulin sensitivity." (PMID 35769086, 2022). "Our results suggest a working model where obesity induces renal HA accumulation and CD44 and RHAMM expression, which activates the TGF-β1/Smad2/3, P38/JNK MAPK, and ROCK2/ERK/Akt pathways, promoting transcription of profibrotic and proinflammatory genes and contributing to the development of ORKP." (PMID 41301516, 2025). "It is noteworthy that different from adipose tissues where ROCK2 appears to the major isoform contributing to ROCK activity, ROCK1 is reportedly the major isoform in liver and mediating diet-induced obesity and insulin resistance through the ROCK1/AMPK signaling pathway." (PMID 35769086, 2022).
pancreatic adenocarcinoma (6 papers, 2017 to 2024). "LncRNA ZFAS1 influences pancreatic adenocarcinoma metastasis through RhoA/ROCK2 signaling pathway by functioning as ceRNA for miR-3924, which itself inhibits ROCK2 expression." (PMID 37464436, 2023). "Our results demonstrated the promotive effect of ZFAS1 on pancreatic adenocarcinoma metastasis and suggested its potential role as a novel regulator of ROCK2." (PMID 32550827, 2020).
Stroke (6 papers, 2016 to 2024). Sudden impairment of blood flow to a part of the brain due to occlusion or rupture of an artery to the brain. "There is a sex difference in CBF outcomes following stroke in this model of PT stroke in the somatosensory cortex, in which ROCK2 appears to be implicated." (PMID 38164600, 2024). "Rock2 haploinsufficiency in intact female mice was associated with interesting differences in CBF following PT stroke." (PMID 38164600, 2024). "Additionally, behavioral testing could provide valuable insight into how ROCK2 deletion and/or loss of gonadal hormones may influence post-stroke recovery." (PMID 38164600, 2024). "When comparing genotypes of female mice, intact Rock2+/− females displayed significantly higher average CBF compared with their intact WT counterparts during the 30 min period following PT stroke induction." (PMID 38164600, 2024). "It is possible that increased RhoA/ROCK signaling in platelets in Rock2+/− females activates thrombus formation during PT stroke induction, resulting in faster vessel occlusion and therefore decreased CBF in these mice." (PMID 38164600, 2024). "The most remarkable finding is that Rock2+/- female show less of a decrease in the blood flow post-stroke compared to intact WTs in short term." (PMID 38164600, 2024). "This is likely due to mechanistic differences in stroke induction, where both ROCK2 and endogenous female sex hormones, most likely estrogen, mediate platelet aggregation and thrombus formation resulting in delayed obstruction of the vessels in the infarct." (PMID 38164600, 2024). "CBF was characterized by LDF immediately following stroke and up to one week in intact and gonadectomized male and female Rock2+/− mice and their WT littermates." (PMID 38164600, 2024). "Intact Rock2+/− females also showed a significant decrease in CBF 48 h post-stroke compared to intact WT females." (PMID 38164600, 2024). "We thus demonstrate clear sex differences in acute CBF outcomes following stroke in a mouse model of PT stroke, a phenomenon in which ROCK2 and gonadal sex hormones appear to be play a role." (PMID 38164600, 2024). "MiR-30c-5p attenuates pathological pathways such as mitogen-activated protein kinases by targeting ROCK2, which presents a novel therapeutic target, miR-30c/ROCK2, in the pathogenesis of stroke." (PMID 36613480, 2022). "In summary, we have shown in vitro that ROCK-2 is the dominant isoform in cells of the BBB, playing an important role in barrier function loss during stroke-like conditions and particularly contributing to BBB impairment by rt-PA and plasmin." (PMID 28510599, 2017). "Both miR-139 and miR-335 are closely associated with stroke-induced angiogenesis via ROCK1 and ROCK2 signalling (both ROCK1 and ROCK2 are VEGF signalling regulators)." (PMID 27275837, 2016). "Both intact and Ovx Rock2+/− females showed significantly reduced CBF at 48 h post-stroke." (PMID 38164600, 2024). "The current study investigates the cerebral blood flow changes following photothrombotic stroke using LDF starting immediately following stroke and up to one week following stroke in intact and gonadectomized male and female ROCK2+/- mice and their WT littermates." (PMID 38164600, 2024). "Furthermore, as observed in intact WT males, intact Rock2+/− males also showed a significant decrease in CBF 48 h post-stroke." (PMID 38164600, 2024). "Hence, selective ROCK-2 inhibition may theoretically be ideal also for antagonism of pericyte-triggered vasoconstriction of brain vessels during stroke." (PMID 28510599, 2017). "Alternatively, intact Rock2+/− females showed a significant difference in CBF values compared with intact WT females, displaying higher CBF values immediately post-stroke and showing a maximal CBF drop 48 h post-stroke." (PMID 38164600, 2024). "Both intact Rock2+/− males and females showed a significant drop in CBF 48 h post-stroke, with similar patterns at other time-points." (PMID 38164600, 2024).
Stroke (continued). "Contrary to what was observed in WT mice, removal of gonadal hormones prior to stroke induction in Rock2+/− mice did not alter CBF outcomes in either males or females." (PMID 38164600, 2024). "Removal of gonadal sex hormones in Rock2+/− males did not change the CBF response to stroke in the hyperacute phase." (PMID 38164600, 2024). "Removal of gonadal sex hormones in Rock2+/− females did not change the CBF response to PT stroke in the hyperacute phase." (PMID 38164600, 2024). "No statistical difference was detected in CBF following PT stroke between intact Rock2+/− males and intact Rock2+/− females, yet a trend toward higher CBF could be observed in females during the hyperacute phase." (PMID 38164600, 2024). "Interestingly, despite no change in protein levels of ROCK1 and ROCK2, overall ROCK activity appeared elevated in intact WT males 48 h post-stroke." (PMID 38164600, 2024). "The opportunity to selectively inhibit ROCK-2 by KD025 may provide a plausible solution, as KD025 was shown to retain the beneficial consequences of ROCK inhibition in rodent stroke without significant hypotensive issues." (PMID 28510599, 2017). "Hence, selective ROCK-2 inhibition by KD025, in contrast to a nonselective ROCK inhibition strategy, has a potent capacity to antagonise the actions of rt-PA and plasmin on the BBB under stroke-like conditions." (PMID 28510599, 2017).
depression (5 papers, 2014 to 2020). "Direct associations considering the expression of ROCK2 and mood disorders are limited; one report showed that placental ROCK2 is down-regulated in women with depression." (PMID 32245436, 2020). "The effects of ROCK2 inhibition were evaluated in the CUMS-induced animal model of depression by applying fasudil (Fas, 20 mg/kg) and baicalin (BA, 30 or 60 mg/kg)." (PMID 31068571, 2019). "We evaluated the effect of NHE1 in animal models of depression and explored ROCK2 inhibition as a neuroprotective strategy against neuronal apoptosis." (PMID 31068571, 2019). "In our present study, we first investigated the effects of ROCK2 inhibition in a CUMS-induced animal model of depression." (PMID 31068571, 2019). "Furthermore, it seems that the use of SSRIs intensifies the alterations in ROCK2 expression compared to depression." (PMID 25628539, 2014). "As shown from our results, CUMS exposure increased the levels of ROCK2 expression and NHE1 expression in the hippocampus of animals with depression-like behaviours." (PMID 31068571, 2019). "In our study, ROCK2 inhibition suppressed the expression of calpain in CUMS-treated mice, suggesting the involvement of calpain in depression." (PMID 31068571, 2019). "In the present study, by incorporating a depressed group of women as additional controls to the SSRI users we are able to show additive effects by depression and SSRI use on certain aspects of NGF signaling (ROCK2 and phosphorylated ROCK2)." (PMID 25611484, 2015). "To further demonstrate the pathogenesis of NHE1-regulated depression, we employed LPS to induce depressive-like symptoms in mice because LPS could activate NHE1, which is related to the activation of ROCK2 and excessive aggregation of Ca2+ in the cytoplasm." (PMID 31068571, 2019). "In conclusion, inhibition of ROCK2 may be a neuroprotective strategy against neuronal apoptosis, and NHE1 may be a potential therapeutic target in depression." (PMID 31068571, 2019). "Thus ROCK2 inhibition could be proposed as a neuroprotective strategy against neuronal apoptosis, and NHE1 might be a potential therapeutic target in depression." (PMID 31068571, 2019). "Although ROCK2 is preferentially expressed in the brain, whereas ROCK1 is primarily expressed in the non-neuronal organs, a role for ROCK1 in depression cannot be completely ruled out." (PMID 31068571, 2019).
lung carcinoma (5 papers, 2016 to 2025). "Little is known about the role of ROCK2 in chemotherapy-induced EMT in lung cancer." (PMID 27229528, 2016).
neuroblastoma (5 papers, 2018 to 2022). Neuroblastoma (NB) is the most common solid, extracranial childhood tumor. "Further, administration of metformin during I/R injury in Neuro2a cells, another neuroblastoma cell line, was shown to reduce the expression of H19 and Rho-associated protein kinase 2 (Rock2), which protects from cellular damage." (PMID 35946958, 2022). "In fact, genes controlling the activity of ROCKs are mutated in approximately 30% of neuroblastoma and high ROCK2 expression in neuroblastoma tumors corresponds to poor patient survival." (PMID 32244473, 2020). "HA1077, a ROCK1 and ROCK2 inhibitor with a higher preference for ROCK2, was studied in several neuroblastoma cell lines and resulted in significant suppression of cell growth." (PMID 30326621, 2018). "ROCK2 has also been shown to inhibit neuronal differentiation in neuroblastoma, as both knockdown of ROCK2, and a novel ROCK2 inhibitor increases neurite outgrowth." (PMID 29880876, 2018).
ovarian carcinoma (5 papers, 2016 to 2025). A malignant neoplasm originating from the surface ovarian epithelium. "And through the correlation analysis of the expressions of ECT2 and RHOA, ROCK1, and ROCK2 in ovarian cancer samples in TCGA database, it was found that the expression of ECT2 was significantly positively correlated with RhoA, ROCK1, and ROCK2." (PMID 40655948, 2025).
renal fibrosis (5 papers, 2020 to 2022). A final common manifestation of a wide variety of chronic kidney diseases characterized by glomerulosclerosis and tubulointerstitial fibrosis. "miR-455-3p overexpression suppressed renal fibrosis through repressing Rho-associated protein kinase 2 (ROCK2) expression." (PMID 33708992, 2021). "In addition, the overexpression of miR-455-3p in STZ-induced DN rats cannot only improve renal fibrosis but reduce inflammatory cytokines by targeting rho-associated coiled coil-containing protein kinase 2 (ROCK2)." (PMID 33883002, 2021). "ROCK2 knockdown, which is regulated by miR-455-3p, suppressed renal fibrosis in DN, but it appears that the role of ROCK2 in the regulatory mechanism of diabetic heart disease is complex, referring to the phosphoinositide-dependent kinase-1/AKT signaling pathway." (PMID 33817282, 2020). "Kaempferol showed the potential to improve histological changes and renal fibrosis while reducing the expression levels of TGF-β1, CTGF, fibronectin, collagen IV, IL-1β, RhoA, ROCK2, and P-MYPT1 in DKD renal tissue." (PMID 36466094, 2022).
rheumatoid arthritis (5 papers, 2020 to 2025). A chronic, systemic autoimmune disorder characterized by inflammation in the synovial membranes and articular surfaces. "It has been observed in a rheumatoid arthritis study that NEAT1 is able to activate the ROCK2 and WNT pathway by inhibiting miR-144-3p." (PMID 38001964, 2023). "It has been shown that oral administration of the selective ROCK2 inhibitor KD025 to healthy subjects or rheumatoid arthritis patients attenuates the ability of T cells to secrete IL-17 in response to stimulation ex vivo via a STAT3-dependent mechanism." (PMID 33613511, 2020). "This NEAT1/miR-144–3p/ROCK2 regulatory pathway may become a new treatment target for rheumatoid arthritis." (PMID 35004702, 2021). "ROCK2 inhibition significantly diminished STAT3 phosphorylation and binding to IL-17 and IL-21 promoters and reduced interferon regulatory factor 4 and nuclear hormone RORyt protein levels in T cells derived from healthy subjects or rheumatoid arthritis patients." (PMID 33613511, 2020).
arteriosclerosis (4 papers, 2014 to 2023). A vascular disorder characterized by thickening and hardening of the walls of the arteries. "The ROCK1 and ROCK2 immunohistochemical staining was performed in our study to demonstrate the link between the upregulated ROCKs expression and arteriosclerosis." (PMID 28050227, 2016). "Among these genes, ROCK2 has been widely studied in arteriosclerosis and vascular smooth muscle cells, indicating that in ASO, ROCK2 may be involved in the microRNA-30a-3p functional process and may be a microRNA-30a-3p direct target gene." (PMID 37899171, 2023).